IL6 (interleukin 6)
Diseases named in the same sentence as IL6 in open-access papers (continued):
Sharing a sentence is not in itself a finding about the gene and the disease.
COVID-19 (continued). "Our results further supported an positive association between elevated IL-6 levels and VTE among patients with COVID-19." (PMID 38493138, 2024). "Individuals who received dexamethasone had significantly lower levels of TNFα, IL6 and IL1β by 21–24 weeks in multivariable analyses, in contrast to findings at 9–12 weeks after COVID-19 onset." (PMID 39008486, 2024). "Given its pivotal role, the IL-6 inhibitor tocilizumab has been widely used in treating COVID-19-related ARDS." (PMID 39479463, 2024). "The overall results highlight not only the influence of IL6 in COVID-19 but also suggest that cross-layer interactions involving IL6 influence clinical heterogeneity, thus influencing the dynamics of disease severity." (PMID 39040605, 2024). "Furthermore, alterations in the oral microbiome have been seen in COVID-19 patients including a reduced diversity, especially in older patients, and bacteria associated with periodontal disease have been shown to stimulate IL-6 and TNF-α production by immune cells." (PMID 39345212, 2024). "As has been reported in HICs, concentrations of IL-6 and other pro-inflammatory mediators were significantly lower in COVID-19 compared to other severe respiratory infections." (PMID 38368384, 2024). "A meta-analysis of 25 COVID-19 studies reported an average IL-6 concentration of approximately 36.7 pg/mL." (PMID 39458339, 2024). "The significantly increased IL-6 level in COVID-19 patients was found to closely correlate with acute respiratory distress syndrome (ARDS) severity and outcome." (PMID 38164360, 2024). "Our findings support the impact of these unique characteristics on long-term immune-related COVID-19 outcomes in HD patients, shown by significant differences in IL-6 and IL-17 concentrations between convalescent HD patients and non-CKD controls." (PMID 38424126, 2024). "Several studies have demonstrated that IL-6 is a key initiator of the cytokine storm in COVID-19-related lung injury, with IL-6 levels directly correlated with patient outcomes." (PMID 39479463, 2024). "Since the COVID-19 pandemic, many trials have found that the COVID-19 group had higher levels of IL-1, IL-6, and IL-10 than the control group." (PMID 38455049, 2024). "A randomized clinical study showed that the use of β-1,3-1,6 glucans derived from the black yeast Aureobasidium pullulans decreased IL-6 levels in COVID-19 patients." (PMID 38612615, 2024). "Previous study showed that the levels of tryptophan were significantly decreased in COVID-19 patients and were inversely correlated with IL-6 levels." (PMID 38799469, 2024). "Further, previous studies about IL-6 have shown a high predictive value in early detection of AKI in critically ill COVID-19 patients, whereas bio-ADM was correlated in only two studies to date regarding this endpoint." (PMID 38336628, 2024). "BMI of patients with severe COVID-19 was higher, whereas age, sex distribution, AP, IL-6, and lactate were similar among the two groups." (PMID 38791005, 2024). "Although levels of IL-6, ferritin and LDH can be higher in COVID-19 patients, their associations with VTE require further exploration." (PMID 38493138, 2024). "Many pro-inflammatory markers increase during COVID-19, including IL-6 and MCP-1, which are key factors for the cytokine storm and acute inflammation caused by COVID-19 and contribute to chronic inflammation caused by NAFLD/NASH." (PMID 38397885, 2024). "One of the clinical features of COVID-19 is the hyperinflammatory activity that is characterized by high expression of IL-6, IL-8 and several other cytokines, chemokines and growth factors." (PMID 39770027, 2024). "Recent clinical studies have shown that the administration of nintedanib in patients with COVID-19 results in a reduction in the production of IL-1 and IL-6." (PMID 37742314, 2024). "Both drugs have shown effectiveness in individuals infected with COVID-19, highlighting the crucial therapeutic role of IL-6 blockade." (PMID 38612744, 2024).
COVID-19 (continued). "Before the onset of the COVID-19 pandemic, IL-6 detection was exclusively conducted at the Immunology Laboratory of Careggi University Hospital using ELISA." (PMID 38617587, 2024). "The current study aims to investigate the predictive value and diagnostic potential of interleukins IL-10, IL-17A, IL-1β, IL-6, CXCL, and MCP for severe COVID-19 and COVID-19 mortality." (PMID 39062105, 2024). "EVs from severe COVID-19 patients had higher levels of IL-6, a proinflammatory cytokine, compared with those from healthy controls." (PMID 39475319, 2024). "This is consistent with other studies that report elevated IL-6, D-dimer, LDH, and CRP levels in severe COVID-19 cases, independently of specific viral mutations." (PMID 39861827, 2024). "The current study focuses on IL-6 and CRP as potential biomarkers for PCC, as IL-6 is centrally involved in COVID-19 pathology as a pro-inflammatory marker and CRP is a sensitive marker of inflammation (Luan, Yin & Yao, 2021)." (PMID 39056056, 2024). "As systemic trans-signalling dominates in acute inflammatory responses such as sepsis and COVID-19, all further in vitro experiments were performed with the combination of IL-6 (1 ng/ml) and sIL-6R (50 ng/ml)." (PMID 38598083, 2024). "Previous reported modification in severe forms of COVID-19 showed increased levels of C-reactive protein, interleukin-6, and D-dimers to predict mortality in hospitalized COVID-19 patients." (PMID 40376291, 2024). "Other pro-inflammatory markers such as procalcitonin, IL-6, and erythrocyte sedimentation rate were positively correlated with COVID-19 severity." (PMID 39504070, 2024). "As valuable biomarkers, LDH and IL-6 levels are positively correlated with disease severity, thus are effective in surveillance of critical COVID-19 patients." (PMID 38493138, 2024). "To facilitate clinical application, we developed a nomogram using age, IL-6 levels, COVID-19 vaccination doses, and comorbidities to predict serum IgG levels for the first time." (PMID 39717543, 2024). "In the context of the cytokine storm the takes place in severe COVID-19 patients, the Interleukin 6 (IL6) pathway emerges as one of the key pathways involved in the pathogenesis of this hyperinflammatory state." (PMID 39346556, 2024). "Among the markers, IL-6 and MCP exhibited statistically significant associations with severe COVID-19 outcomes." (PMID 39062105, 2024). "IL-6 remains a key molecule of the cytokine storms characterizing COVID-19, exerting both proinflammatory and anti-inflammatory effects." (PMID 39518964, 2024). "This is the first study to our knowledge that investigates the prognostic value of bio-ADM compared to IL-6 measured at hospital admission in COVID-19 patients." (PMID 38336628, 2024). "A recent meta-analysis showed that IL-6 blockade with tocilizumab works best for moderate to severe COVID-19." (PMID 38598083, 2024). "A previous study showed that severely ill patients with COVID-19 have a high concentration of pro-inflammatory cytokines, such as interleukin-6 (IL-6), compared to those who are moderately ill." (PMID 39483459, 2024). "The ability of recombinant, SARS-CoV-2 Spike (S) protein to modulate the production of two COVID-19 relevant, pro-inflammatory cytokines (IL-6 and IFN-γ) in PBMC cultures of healthy, pre-COVID-19 subjects was investigated." (PMID 38675840, 2024). "Numerous studies have demonstrated that IL-10 and IL-6 are important factors for predicting the exacerbation of COVID-19 and are significantly positively correlated with the severity of disease and the mortality rate of patients with COVID-1912,46,47." (PMID 38710800, 2024). "In contrast, in survivors of COVID-19, the levels of cytokines/chemokines in serum decreased significantly before recovery, and the serum IL-6 concentration returned to normal levels before discharge." (PMID 39654886, 2024).
COVID-19 (continued). "A Ghanian study of COVID-19 patients also found low levels of IL-6 in the study cohort than in the European cohort in early phase of disease." (PMID 39528988, 2024). "High plasma levels of IL-6 are known to be associated with adverse clinical outcomes, including ICU admission, ARDS, mechanical ventilation and death among COVID-19 patients." (PMID 38933109, 2024). "IL-6 is a proinflammatory cytokine proposed as an inflammatory biomarker for COVID-19 severity and is an activator of the JAK-STAT signaling pathway." (PMID 38603606, 2024). "In the CoVonly group receiving only the third booster dose of COVID-19 vaccine, we found, on 1 day (d1) post-immunization, a strong increase of the cytokines IL-15, IL-6, TNF-α and IFN-γ as well as of the chemokine CXCL10." (PMID 39340080, 2024). "In 2023, the authors further revealed that the excessive production of IL-10 and IL-6, coupled with reduced TGF-β levels, has been associated with cytokine storm-related fatalities in severe cases of SFTS and critically ill COVID-19 patients." (PMID 38389047, 2024). "Critical COVID-19 cases presented with increased levels TG, fasting glucose, procalcitonin, C-RP, D-dimer, and IL-6 (p < 0.01 for all) and lower levels of high-density lipoprotein (p = 0.003) compared with noncritical cases." (PMID 38449886, 2024). "The pathogenesis of COVID-19 involves intense inflammatory responses and encompasses a complex array of mediators, including IL-6, IL-8, and IL-10." (PMID 39654886, 2024). "In our study, IL-6 level was significantly higher in COVID-19 patients compared to healthy individuals." (PMID 39685929, 2024). "Few studies provide data on cytokines in children with severe/critical COVID-19 cases, but the most frequently reported elevated cytokines were IL-6 and IFN-γ." (PMID 39596272, 2024). "This was guided by findings that showed significant elevation of markers such as IL-6 and chemokines in COVID-19 intensive care unit (ICU) patients." (PMID 38474155, 2024). "Previous studies have demonstrated alterations in the structural and functional proteins of RBCs in patients with COVID-19, correlated with disease severity and inflammatory markers such as interleukin-6." (PMID 38543504, 2024). "In our present study, the ACLF+COVID-19 group had significantly higher IL-6 levels, and the IL-6 level was positively correlated with Meld-Na score, AARC score, and SOFA score." (PMID 39867341, 2024). "In this study, we investigated the association between baseline level of IL-6 and risk of ACS development in a cohort of hospitalized patients with COVID-19 during pandemic." (PMID 39395941, 2024). "The study underscores the limited predictive value of traditional demographic and clinical factors for ICU mortality in COVID-19 patients, highlighting the critical role of dynamic immune response markers like Il-6 and WBC counts." (PMID 38935767, 2024). "Evidence suggests enhanced serum IL-6 levels in severe COVID-19 subjects compared to mild-moderate COVID-19 patients." (PMID 38675414, 2024). "Research suggests a correlation between IL6 levels and altered metabolite levels including amino acids, fatty acids, and lipids among severe COVID-19 patients." (PMID 39040605, 2024). "IL-6, a vital inflammatory cytokine in the development of COVID-19, leads to acute lung injury, acute respiratory distress syndrome (ARDS), and further tissue damage." (PMID 38104038, 2024). "In the case of COVID-19, the singular blockade of IL-6 already appears to be close to achieving this goal." (PMID 38598083, 2024). "It has been noted that IL-6 levels are significantly elevated in COVID-19 individuals and are directly correlated with disease severity." (PMID 37742314, 2024). "A recent systematic review suggests that although there is no hard evidence to support the use of hemoperfusion in patients with COVID-19, most studies describe a decrease in IL-6 levels after hemoperfusion." (PMID 38217010, 2024).
COVID-19 (continued). "In our series, we found that serum concentrations of the pro-inflammatory cytokine IL-6 were significantly higher in COVID-19 patients than in healthy controls." (PMID 38731010, 2024). "A likely association between arrhythmic events and cytokine bursts, including IL6, was suggested in patients with autoimmune diseases and, more recently, in subjects hospitalized for severe COVID-19." (PMID 39596280, 2024). "This study identified 30 nodes associated with cytokine storm, ARDS, and inflammatory process of COVID-19, namely, IL-6, IL-6R, NF-κB, IL-2, IL-2RA, IFNA2, IFNAR1, COX5A, and COX411." (PMID 39640429, 2024). "Individuals with symptomatic COVID-19 had higher levels of four cytokines (IL-6, IFN-γ, TNF-α, and IL17) than healthy controls." (PMID 38459174, 2024). "The results showed that 30 protein nodes played a significant role in COVID-19 cytokine storm and eight active compounds had interactions with IL-6." (PMID 39640429, 2024). "NAR can not only reduce the lung injury induced by COVID-19 by inhibiting interleukin-6 (IL-6), but also block LPS-induced pulmonary edema by inhibiting the secretion of MPO, tumor necrosis factor-α (TNF-α) and neutrophil infiltration." (PMID 38755662, 2024). "An exaggerated immune response, accompanied by increased IL-6 levels, is commonly observed in COVID-19 patients, leading to widespread inflammation and damage to organs, including the liver." (PMID 39759701, 2024). "IL6 is an essential cytokine that increases in patients with COVID-19 at all stages of the disease and at all severity levels that ends with cytokine storm syndrome, and fatal acute respiratory distress syndrome and other organ failure." (PMID 39729489, 2024). "We found that IL-8, IL-6, and IP-10 were the most highly upregulated in all COVID-19 community and hospital groups relative to healthy participants, indicating that their upregulation is a hallmark of all SARS-CoV-2 infections." (PMID 39650666, 2024). "Increased levels of IL-6 in serum can be used as a predictor of COVID-19 progression; hence, blocking this protein is considered an effective treatment to prevent cytokine storm and ARDS." (PMID 39640429, 2024). "An increased IL-6 level was described as one of the promising biomarkers predicting mortality in COVID-19-related ARDS." (PMID 39767830, 2024). "In severe COVID-19, high levels of pro-inflammatory cytokines have been observed, such as IL-1, IL-6, IL-8, IL-12, IL-17, TNF-α and IFN-γ." (PMID 39596272, 2024). "The actions induced by high levels of IL-6, IFN-α, TNF-α have been associated with persistence and dysfunction of severe COVID-19 and with a greater probability of death." (PMID 38424312, 2024). "In our study, we analyzed twenty inflammatory cytokines in patients with cancer and COVID-19 and found that IL-6 stood out due to showing the most significant variations across the spectrum of COVID-19 severity." (PMID 39272832, 2024). "We found that levels of IL-6 and sIL-6R continued to be significantly increased in COVID-19 patients compared to healthy controls (63.15 ± 18.5 pg/mL vs. 1.91 ± 0.89 pg/mL and 75.21 ± 14.29 ng/mL vs. 26.51 ± 8.16 ng/mL, respectively)." (PMID 39063569, 2024). "Consistent with our findings, inhibition of ITGα5 decreased EC permeability and IL-6 secretion in COVID-19 patients." (PMID 38853850, 2024). "Other inflammatory biomarkers, including CRP and IL-6, have been extensively investigated and used in daily in-hospital practice for patients with COVID-19." (PMID 38982355, 2024). "A recent study showed that among ICU patients with COVID-19, administration of imatinib decreased extravascular lung water when IL-6, TNF-R1 and SP-D levels are increased." (PMID 38396460, 2024). "Specifically, in the context of COVID-19, a robust inflammatory response is present, as evidenced by elevated levels of IL-1 beta, IL-6, and TNF-alpha." (PMID 39511501, 2024).
COVID-19 (continued). "It has been shown that proinflammatory cytokines and chemokines, including IL-1β, TNF-α, IL-6, interferon gamma-induced protein-10, monocyte chemoattractant protein-1, and macrophage inflammatory proteins 1-α, were significantly elevated in COVID-19 patients." (PMID 39195168, 2024). "Interleukin (IL)-6 concentrations were significantly increased in COVID-19 patients (p < 0.0001 vs. controls), and negatively correlated with the absolute counts of circulating CD1c+ cDC2 (r = −0.29, p = 0.034) and CD303+ pDC (r = −0.29, p = 0.036) subsets." (PMID 38731010, 2024). "Cytokine storms, characterized by excessive release of inflammatory cytokines like IL-1β, TNF-α, IL-6, and IFN-γ, are associated with severe COVID-19 and can suppress the HPT axis, leading to decreased TSH secretion." (PMID 40735669, 2024). "Concerning neuroinflammatory process, cytokines TNF-α (tumor necrosis factor) and IL-6, which are upregulated in COVID-19, are also present in major depressive disorder and Alzheimer’s disease." (PMID 38313024, 2024). "In fact, COVID-19 patients with cardiovascular co-morbidities had IL-6 levels comparable with those in healthy individuals." (PMID 39518552, 2024). "In this study, the AUC for IL-6 in predicting the viral shedding time by 10 days among COVID-19 patients was 0.533, with both specificity and sensitivity lower than SII." (PMID 40376291, 2024). "COVID-19 patients with CVD who were taking statins had significantly lower median concentrations of IL-6 (21 vs. 44 pg/mL, p = 0.027), TNFα (21 vs. 39.5 pg/mL, p = 0.036), and IL-10 (19 vs. 25.5 pg/mL, p = 0.025) compared to COVID-19 patients with no CVD." (PMID 39518552, 2024). "COVID-19 induces hyperactivity of the immune system, especially interleukin-6 (IL-6), which can lead to thyroid dysfunction due to the disruption of deiodase and thyroid transport nutrients." (PMID 39045269, 2024). "With regard to biomarkers, COVID-19 and TB present elevated levels of C-reactive protein, D-Dimer, and interleukin 6, but also alterations such as leukopenia, neutrophilia or even platelet dysfunctions." (PMID 38793006, 2024). "Subsequently, this result was followed by two inflammatory markers in COVID-19 patients: C-reactive protein and Interleukin-6." (PMID 38702342, 2024). "In COVID-19 patients, high levels of proinflammatory cytokines, including IL-6, correlate with reduced IFN-γ levels, contributing to severe disease outcomes and olfactory disturbances." (PMID 39126095, 2024). "In terms of prognosis, recent studies have shown the value of IL-6 in the prediction of severe COVID-19 at hospital admission." (PMID 39062668, 2024). "The findings of this study clearly highlight the diagnostic potential of IL-6 and MCP as predictors of severe COVID-19, evidenced by their high hazard ratios and significant p-values." (PMID 39062105, 2024). "In patients with severe COVID-19, a high correlation was observed between circulating inflammatory cytokines, such as IL-6, CXCL10 (IP-10), and CSF1 (M-CSF), and arginine metabolism as well as tryptophan metabolism." (PMID 39759510, 2024). "ROC curve analysis showed that interleukin-6 and Presepsin were good markers for prediction of severity of COVID-19 among the diseased children." (PMID 39354444, 2024). "The overexpression of inflammatory adipokines can impair chemotaxis, alter macrophage differentiation, and upregulate inflammatory cytokines such as IL-6 to contribute to the increased morbidity of COVID-19." (PMID 39777148, 2024). "Regarding RAASI, only IL-6 (adjusted p = 0.017) was seen to be significantly lower in the plasma of COVID-19 patients with CVD co-morbidities consuming these medications compared to patients who did not have any CVD." (PMID 39518552, 2024). "Studies have indicated that patients with severe COVID-19 exhibit elevated levels of pro-inflammatory cytokines (IL-6, tumor necrosis factor-α) and anti-inflammatory cytokines (IL-4, IL-10), along with decreased expression of CD4 and CD8 cells." (PMID 39040601, 2024).